OLMALINC (oligodendrocyte maturation-associated long intergenic non-coding RNA)
Synonyms: bA34D15.5; FLJ12974; HI-LNC80; C10orf75; LINC00263; NCRNA00263; OLMALINCAS
Gene: Long non-coding RNA gene on chromosome 10 (100,372,914 to 100,454,043, forward strand). Ensembl gene ENSG00000235823.
Diseases named in the same sentence as OLMALINC in open-access papers:
OLMALINC is named in the same sentence as 16 diseases in open-access papers, as found by Europe PMC text mining. Sharing a sentence is not in itself a finding about the gene and the disease. The quoted sentences say what the papers report.
breast carcinoma (2 papers, 2020 to 2023). "We confirmed that a potential human lncRNA, OLMALINC, plays a similar role in fatty acid metabolism that can be regulated via PTHrP and validated our mouse findings in human breast cancer cell lines." (PMID 37568579, 2023).
gastric cancer (1 paper, 2025). A primary or metastatic malignant neoplasm involving the stomach. "To further assess their clinical relevance, we evaluated the expression of their host genes (OLMALINC, TRHDE-AS1, ZNF436-AS1, AC027045.3) in matched tumor/normal tissues from gastric cancer patients by RT-qPCR." (PMID 39794466, 2025).
cancer (6 papers, 2019 to 2025). A tumor composed of atypical neoplastic, often pleomorphic cells that invade other tissues. "Among the 26 upregulated genes, IFNG-AS1, AC093818.1, AF127936.5, and OLMALINC were expressed in different diseases, especially IFNG-AS1, which has been reported in many malignant tumors." (PMID 37342185, 2023).
OLMALINC also shares sentences with these, for which no sentence is quoted: tumor (3 papers); colorectal cancer (2); lung adenocarcinoma (2); lung carcinoma (2); clear cell carcinomas (1); hepatic carcinoma (1); lung (1); non-small cell lung carcinoma (1); ovarian carcinoma (1); prostate carcinoma (1); renal carcinoma (1); renal cell carcinoma (1); squamous cell carcinoma (1).